MMP9 (matrix metallopeptidase 9)
Diseases named in the same sentence as MMP9 in open-access papers (continued):
Sharing a sentence is not in itself a finding about the gene and the disease.
hemorrhage (28 papers, 2005 to 2026). Loss of blood from the vascular compartment to the exterior or into nonvascular body space as a result of rupture or severance of the blood vessels. "We summarized that SNPs of five inflammatory genes (IL6, APOE, IL1B, IL17A, MMP9) were reported to be associated with bAVM-related hemorrhage." (PMID 37065486, 2023). "We performed a ROC analysis and results showed that a serum MMP-9 level >1,011 ng/ml was associated with spontaneous hemorrhage in adult MMD patients with 70.37% sensitivity and 71.88% specificity (AUC 0.73, 95% CI 0.597–0.864, P = 0.003)." (PMID 34531816, 2021). "A late Suzuki stage (>4) (OR 4.565, 95% CI 1.028–20.280, P = 0.046) and serum concentrations of MMP-9 >1,011 ng/ml (OR 7.218, 95% CI 1.826–28.533, P = 0.005) are risk predictors of hemorrhages in MMD patients." (PMID 34531816, 2021). "Study found that MMP-9 take part in tPA-associated hemorrhage, so the uncontrolled activation of MMP after tPA reperfusion can degrade key proteins in the cerebrovascular system, thereby damaging the structural integrity of the vessels and ultimately leading to vascular rupture." (PMID 35340417, 2022). "We add to these existing data of MMP-9 activity and hemorrhage risk in AIS patients treated with tPA by examining AIS patients with LVO treated with MT, a therapy with much higher reperfusion rates and one which allows the recording of reperfusion status after treatment." (PMID 32582006, 2020). "It is believed that MMP-2 and MMP-9 (matrix metalloproteinase) expression levels interfere with hemorrhage." (PMID 38410133, 2024). "Twelve single nucleotide polymorphisms (SNPs), including IL6 rs1800795, IL17A rs2275913, MMP9 rs9509, VEGFA rs1547651, and EPHB4 rs314353, rs314308, and rs314313, were associated with bAVM-related hemorrhage." (PMID 37065486, 2023). "Treatment with CRO + DOX significantly diminished both the number of cerebral hemorrhages (p = 0.029) and the amount of MMP-9 in the brain (p = 0.046) compared to untreated controls, but not to CRO-treated animals (p > 0.05)." (PMID 32660552, 2020). "Other invasive markers such as MMP-9 and -14 were previously correlated with the hemorrhage and invasive behavior of PitNETs." (PMID 31100921, 2019). "A large proportion of these neutrophils expressed MMP-9 and positively correlated with hemorrhage and hyperemia." (PMID 29752550, 2018). "This led to the identification of statistically significant association between bAVM-related hemorrhage and twelve heritable variants of seven genes (IL6, APOE, IL1B, IL17A, MMP9, EPHB4, and VEGFA) involved in the inflammatory and angiogenic signaling pathways." (PMID 37065486, 2023). "Importantly, Xe-liposomes in combination with late rtPA treatment reduced rtPA-induced hemorrhage, attributing to the reduction of MMP9 immunoreactivity." (PMID 37627321, 2023). "Taken together, the MMP-9 data suggests that active ECM remodeling exists early in hemorrhage and that USSCs produce an anti-inflammatory effect by day 14 which may contribute to less structural remodeling." (PMID 33897371, 2021). "Together, it might be postulated that MMP-9 activity and BBB disorder are associated with the risk of hemorrhage in MMD patients." (PMID 34531816, 2021). "Therefore, it has been hypothesized that the level of MMP-9 might serve as a biomarker for predicting hemorrhage in MA patients." (PMID 34948203, 2021). "The protein levels of IGFBP3, MMP9 and PDGF-BB were significantly higher in the denser haemorrhage group." (PMID 36473885, 2022). "CD163 mRNA expression displayed a weak increasing trend to macrophages, and moderate increasing trends to lipids and intraplaque hemorrhage, as well as to MMP-1 and MMP-9." (PMID 32873809, 2020). "Certainly, MMP-9 has been the most widely studied MMP family member in BBB leakage, leukocyte infiltration, brain edema, and hemorrhage." (PMID 29724240, 2018).
migraine (28 papers, 2011 to 2025). "The systematic review reveals a significant association between NLRP3 and MMP9 expression levels and migraine progression." (PMID 38836002, 2024). "The roles of NLRP3 and MMP9 in migraine pathophysiology not only sheds light on the underlying mechanisms of the disease but also identifies potential therapeutic targets." (PMID 38836002, 2024). "This study delves into the potential roles of NLRP3 and MMP9 as biomarkers in the pathophysiology of migraine, shedding light on the underlying mechanisms of this complex neurological disorder." (PMID 38836002, 2024). "On the other hand, in migraine patients with aura, positive but less pronounced association remains only with MMP-9 (rS = 0.46) and TGF-α (rS = 0.62)." (PMID 36233564, 2022). "Furthermore, the review highlights the inflammatory cascade initiated by NLRP3 activation and subsequent MMP9 release as a potential mechanism underlying migraine pathogenesis." (PMID 38836002, 2024). "It has been suggested that proinflammatory mediators such as COX-2, TNF-α, and MMP9 could be viable pharmaceutical targets in the development of migraines caused by NO." (PMID 38836002, 2024). "Increased plasma MMP-9 has also been implicated in migraine pathogenesis." (PMID 27148260, 2016). "Research shows that plasma MMP-9 level rises considerably in cases of migraine attacks, mostly during headache stages and after termination." (PMID 41357008, 2025). "The expression of activation markers, including MMP-9, IL-6 receptor family molecules, and phosphorylated transcription factors, significantly varied by migraine phase between clusters compared to healthy controls." (PMID 40852402, 2025). "This review summarizes 22 preclinical studies on Nitroglycerin (NTG), NLRP3, MMP9, and related biomarkers in migraine." (PMID 38836002, 2024). "It highlights the interconnected relationships between NLRP3, MMP9, and various other biomarkers, providing a comprehensive overview of their potential contributions to migraine attacks." (PMID 38836002, 2024). "Several key discoveries from this systematic review were emphasized, notably the association between PX7R, RIPK, P2X4 receptor activation, NLRP3, and MMP9 in the genesis of migraines." (PMID 38836002, 2024). "Elevated levels of another member of the MMP family, MMP9, has previously been shown in migraine patients." (PMID 39044165, 2024). "Elevated levels of both NLRP3 and MMP9 are consistently observed in migraine patients compared to controls, suggesting their potential involvement in the pathophysiology of the condition." (PMID 38836002, 2024). "Activation of NLRP3 and upregulation of MMP9 contribute to neuroinflammation, which is increasingly recognized as a key factor in migraine pathogenesis." (PMID 38836002, 2024). "Nowadays, researchers are especially targeting NLRP3 inflammasomes which has a robust connection to migraine and predicting MMP9 additionally playing a major role in the migraine attack." (PMID 38836002, 2024). "This systematic study is motivated by the exploration of the roles of NLRP3 and MMP9 in the onset of migraine attacks." (PMID 38836002, 2024). "This study seeks to investigate the potential connection between NLRP3 and MMP9 in migraine pathology." (PMID 38836002, 2024). "There are two other significant correlations only in migraine patients with aura: the correlation between MMP-9 and IL-8 (inverse) and between IL-8 and sICAM-1 (inverse)." (PMID 36233564, 2022). "TGF-α correlates with PAI-1 (rS = 0.62); with MMP-9 (rS = 0.45), it is less pronounced in migraine patients with aura but remains, and TGF-α with sICAM-1 (rS = −0.30) is also less pronounced." (PMID 36233564, 2022). "Other inflammatory markers associated with vascular diseases, such as Hcy and matrix metalloproteinase-9 (MMP-9), are elevated in migraineurs’ blood, indicating neuroinflammatory cascade activation in migraine pathogenesis." (PMID 34444772, 2021).
migraine (continued). "Collectively evaluated, astrocytes contributed more effectively to the migraine pathology via elevated MMP-9 for regulating BBB integrity." (PMID 33597821, 2021). "An elevation of inflammatory mediators, including MMP-9, and structural changes in pericytes, were detected in patients with migraine." (PMID 34445635, 2021). "Mitochondrial dysfunction, increased calcitonin, matrix metalloproteinase 9 (MMP-9), and nitric oxide (NO) levels, as well as decreased level of metabolic enzymes are also considered among the significant factors generating migraine." (PMID 33375459, 2020). "Increased activity of matrix metalloproteinases in migraine patients is confirmed, which MMP9 action as an initiator for this cascade." (PMID 32231773, 2019). "It is believed that other inflammatory markers associated with vascular dysfunction, e.g. Hcy and matrix metalloproteinase-9 (MMP-9), are elevated in the blood of migraine sufferers." (PMID 27191890, 2016). "TIMP-1 levels were lower in migraine patients; the MMP-9/TIMP-1 ratio was significantly higher." (PMID 41357008, 2025). "The glucocorticoid mechanisms are associated with steroidal anti-inflammatory effects or direct involvement in migraine pathophysiology, such as expression of various MMP-9 inhibitors, reduced blood-brain barrier permeability, production of nitric oxide, and reduction of the level of CGRP." (PMID 41357008, 2025). "Results from 26 selected articles showed that glucocorticoids decreased the expression of matrix metalloproteinase-9 (MMP-9), inhibited nitric oxide synthesis, and reduced calcitonin gene-related peptide (CGRP) levels, all of which are key agents implicated in migraine pathogenesis." (PMID 41357008, 2025). "This hypothesis sets the stage for establishing a robust connection between NLRP3 and MMP9 in the context of migraines." (PMID 38836002, 2024). "However, elevated MMP-9 levels are frequently associated with migraine occurrences, indicating a potential, albeit subtle, role for BBB disruption in migraine pathology." (PMID 39456943, 2024). "After extensive literature reviews and discussions, we concluded that the NTG-inducing model (10 mg/kg) is the most suitable for inducing the production of NLRP3, MMP9, and other proinflammatory molecules in rodents, making it widely accepted as a universal animal model for studying migraines." (PMID 38836002, 2024). "MMP9-mediated disruption of the blood–brain barrier can facilitate the entry of inflammatory cells and molecules into the brain parenchyma, exacerbating neuroinflammation and promoting migraine attacks." (PMID 38836002, 2024). "NLRP3 inflammasome activation and MMP9-mediated neuroinflammation may modulate the susceptibility to CSD, influencing the frequency and severity of migraine attacks." (PMID 38836002, 2024). "Elastase activity and MMP-9 levels are elevated in migraine patients." (PMID 35906498, 2023). "Matrix metalloproteinases, especially the MMP-9, have drawn attention in relation to migraine discomfort because the increased activity may impact the permeability of the blood–brain barrier." (PMID 36982428, 2023). "Moreover, patients experiencing migraine have been found to have significantly higher plasma levels of MMP-9 compared to healthy individuals and those with tension-type headaches." (PMID 37755358, 2023). "PAI-1, TGF, and MMP-9 could be used as potential biomarkers to distinguish migraine patients from healthy individuals." (PMID 36233564, 2022). "The situation is different in migraine patients with aura, where there is one new inverse correlation between MMP-9 and IL-8 (rS = −0.37) and one new direct correlation between MMP-9 and PAI-1 (rS = 0.46), but a correlation with TGF-α is less pronounced (rS = 0.45) than in patients without aura." (PMID 36233564, 2022). "An MMP-9 haplotype was reported to affect circulating MMP-9 levels in women with migraine." (PMID 34445635, 2021).
migraine (continued). "It has been suggested that MMP-9 levels, which were known to peak during the 3rd day of the attack, could be used as a biomarker in migraine, and inhibition of MMP-9 might be an alternative target in treatment." (PMID 33597821, 2021). "While one study on spontaneous migraine with aura observed an increase in matrix metalloproteinase-9 (MMP-9), indicative of a BBB breach, another study in migraine with aura found increased perfusion at the brainstem only and no permeability changes at the cortex." (PMID 30073201, 2018). "MMP-9 plays a role in migraine, and serum levels are generally elevated in migraineurs." (PMID 27148260, 2016). "In addition, the antioxidative nature of CoQ10 reduces the expression of cytokines and matrix metalloproteinase-9 (MMP-9), an enzyme involved in inflammation of nerves that could exacerbate migraine attacks." (PMID 37946741, 2023). "Performed hierarchical cluster analysis, based on an ML modelling approach, reveals a group of three cytokines, PAI-1, TGF-α, and MMP-9, which could be used as potential markers to distinguish migraine patients from healthy individuals or subgroups of migraine patients." (PMID 36233564, 2022). "Studies have observed changes in serum MMP9 levels in patients with migraine in different periods and subtypes and found that serum MMP9 was upregulated during the onset of migraine, which may be one of the potential related mechanisms of migraine." (PMID 34754315, 2021). "It is believed that other inflammatory markers associated with vascular dysfunction, such as homocysteine (Hcy) and matrix metalloproteinase-9 (MMP-9), are also elevated in the blood of individuals with migraine." (PMID 37755358, 2023). "The average plasma MMP-9 levels were highest in subjects who had their blood samples taken between two and four days post their latest attack, implying that the elevated MMP-9 might be an indication of structural damage and subsequent remodeling associated with migraine attacks." (PMID 37755358, 2023). "In an animal model of migraine, the expression of COX-2, MMP9 and TNF-α increased after an NO donor infusion, with expression being more evident in the meningeal blood vessels." (PMID 36614097, 2022). "We also find significant inverse correlations between BMI and MMP-9 (rS = −0.5532, p = 0.0499) and direct correlation between BMI and IFN-γ (rS = 0.6455, p = 0.0172) only in migraine patients with aura." (PMID 36233564, 2022). "Elevations of MMP-9 and ICAM-1, which are considered typical markers suggestive of BBB disorders, are observed in patients with migraine." (PMID 34445635, 2021). "Migraine is a complex neuroinflammatory disorder involving multiple interacting pathways, including CGRP signaling, PACAP regulation, oxidative stress, nitric oxide production, and MMP-9 activation." (PMID 41357008, 2025). "MMP9 is among the biomarkers that might serve as an alternative therapeutic target to disrupt BBB integrity in astrocytes, and its role in migraine pathogenesis is of significant importance to explore." (PMID 38836002, 2024). "MMP-9 shows only one inverse correlation with sICAM-1 (rS = −0.40) in healthy subjects, and this correlation remains in migraine patients without aura (rS = −0.37)." (PMID 36233564, 2022). "A relationship between MMP-9 and cellular iron homeostasis in glial cells in migraine pathophysiology has not yet been disclosed." (PMID 33597821, 2021). "According to one study, plasma levels of MMP-9 should not be used as a biomarker of migraine with aura." (PMID 25339863, 2014). "Indirect evidence: patients presenting migraine without aura showed increased plasma concentrations of MMP-9 concentrations than migraine with aura patients." (PMID 25339863, 2014). "When measured in isolation, MMP-9 levels appears to be the same for migraine patients with and without aura." (PMID 22970361, 2012).
migraine (continued). "In patients suffering from migraine without aura, however, the ratio of MMP-9 to TIMP-1 was increased compared to patients with aura, reflecting a potential distinct pathophysiological mechanism." (PMID 22970361, 2012). "Nonetheless, the participation of MMP-9 in the migraine pathophysiology is not completely accepted." (PMID 25339863, 2014). "Several other correlations between cytokines are more pronounced in migraine patients without aura than in patients with aura: between PAI-1 and MMP-9 (direct); between MMP-9 and PAI-1 (direct), and TGF-α (direct); as well as between sVCAM-1 and IL-8." (PMID 36233564, 2022). "Many correlative relationships between PA-1 and other cytokines are found: positive with MMP-9 (rS = 0.77), TGF-α (rS = 0.82), and MCP-1 (rS = 0.33), and negative one with sICAM-1 (rS = −0.72) in migraine patients without aura." (PMID 36233564, 2022). "The most correlations between cytokines are in migraine patients only without aura, such as correlations between MPC-1 and PAI-1 (direct correlation), MMP-9 (direct), sICAM-1 (inverse), and sVCAM-1 (inverse)." (PMID 36233564, 2022). "TGF-α shows two pronounced direct correlations with PAI-1 (rS = 0.82), and with MMP-9 (rS = 0.71), and one inverse correlation between TGF-α and sICAM-1 (rS = −0.45) in migraine patients without aura." (PMID 36233564, 2022). "There are three correlations in migraine patients with aura that are absent in patients without aura: between IL-8 and PAI-1; MMP-9 and IL-8; and IL-8 and sICAM-1." (PMID 36233564, 2022). "Although the activation of MMP-9 has not been definitively proven in migraine patients, the exact mechanisms by which MMP-9 contributes to the development or maintenance of migraine attacks remain unclear." (PMID 41357008, 2025). "Hierarchical cluster analysis shows that three cytokines, PAI-1, MMP-9, and TGF-α, can form a response similar (subcluster) in both groups of patients with migraine (without aura and with aura) compared with healthy people without migraine." (PMID 36233564, 2022). "Also, other correlations between cytokines are only in migraine patients without aura: between PAI-1 and sICAM-1 (inverse); between MMP-9 and sICAM-1 (inverse); and between TGF-α and PAI-1 (direct), MMP-9 (direct), and sICAM-1 (inverse)." (PMID 36233564, 2022).